ETV6 (ETS variant transcription factor 6)
Diseases named in the same sentence as ETV6 in open-access papers (continued):
Sharing a sentence is not in itself a finding about the gene and the disease.
tumor (continued). "In their models, which are supported by our data, ETV6 acts as a tumour suppressor gene that negatively regulates the epithelial–mesenchymal transition and disease progression in PCa cells." (PMID 37239316, 2023). "The tumor suppressors ETV6, CEBPA, IRF8, and IRF1 are among the lineage-controlling master TFs found in CD141-positive monocytes enriched with SE-associated genes upregulated by cortistatin A." (PMID 37501079, 2023). "Similar to other tumor types, TPM3::NTRK1, EML4::NTRK3 and ETV6::NTRK3 fusion variants represented the majority of NTRK1–3 translocations identified in this study." (PMID 37686416, 2023). "Nine tumors harbored an NTRK1 fusion with different fusion partners (4 × TPM3, 4 × LMNA, 1 × SFPQ), one tumor harbored an ETV6::NTRK3 fusion." (PMID 37067589, 2023). "To investigate this, we focused on a transcriptional factor called Ets variant 6 (ETV6), the expression of which was high in both GBM tumor core and fetal astrocytes when compared to normal mature astrocytes." (PMID 36292767, 2022). "In both healthy donors, EpiTCer-loaded DC induced an increased frequency of CD8+ tumor-specific T cells compared to ETV6 and NUP210 peptides delivered separately or in pools." (PMID 35433456, 2022). "According to our previous study, ETV6 was one of the top upregulated genes in both GBM tumor core and fetal astrocytes compared to normal mature astrocytes." (PMID 36292767, 2022). "ANRU imDC were loaded with tumor lysate, ETV6 or NUP210 9mer peptides, or several ratios of EpiTCer beads." (PMID 35433456, 2022). "A ChIP-Seq study using NPC tumor tissues and xenografts targeting H3K27ac identified a distinct group of super enhancers (SE), among which an oncogene, ETV6, was further demonstrated to be up-regulated and correlated with poor survival in NPC patients." (PMID 33718209, 2021). "The most common tumour type with ETV6 was salivary gland (36.8%), with TPM3 was CRC (29.3%) and with LMNA was CRC (39.4%)." (PMID 34285332, 2021). "Tumour cells showed higher levels of apoptosis, lower proliferation rate and a greater sensitivity to PI3K inhibitors in vitro along as a decrease in tumour growth in xenografts models after ETV6/RUNX1 fusion gene abrogation." (PMID 31952221, 2020). "CRKL, ETV6 acts as tumor promotors and miR-429 acts as a tumor suppressor in HCC, their dysexpressions are involved in the carcinogenesis and progression of hepatocarcinoma." (PMID 32326970, 2020). "Our results demonstrated that ETV6 as a tumor promoter in the development and progression of hepatocarcinoma." (PMID 32326970, 2020). "On the other hand, similar to antecedent studies, the more frequently altered genes were related to cell cycle regulation (ETV6), tumor suppression (CDKN2A/B), apoptosis regulation (BTG1) and others." (PMID 32607130, 2020). "Our results indicated that ETV6 acts as a tumor promoter in hepatocarcinoma by promoting the aggressiveness of tumor cells." (PMID 32326970, 2020). "A representative image of immunofluorescence staining of a primary uterine serous tumor shows protein level nuclear localization of ETV6 in tumor cells." (PMID 31554806, 2019). "Given that deletion or inactivation of ETV6 has been frequently observed in hematopoietic malignancies, ETV6 is also considered to be a tumor suppressor." (PMID 30478527, 2019). "Based on our aggregated results, we propose a working model that disruption of ETV6 contributes to tumor progression and TKI-resistance through derepression of TWIST1 and activation of EGFR-RAS signaling." (PMID 29455655, 2018). "Our results provide a molecular mechanism by which ETV6 suppresses tumor progression through transcriptional regulation of TWIST1 and disruption of EGFR-RAS signaling." (PMID 29455655, 2018). "Our results support a model that the EGFR facilitates tumor malignancy by reducing ETV6, which enhances TWIST1 activities." (PMID 29455655, 2018).
tumor (continued). "In summary, we concluded that ETV6-knockdown leads to derepression of TWIST1 which contributes to tumor progression." (PMID 29455655, 2018). "When simulating the metastasis process by delivering this pair of cells into mice by an intracardiac injection, ETV6-knockdown indeed reduced the life expectancy and promoted metastasis according to tumor masses detected in the brain (arrow)." (PMID 29455655, 2018). "Further CI1033 treatment in mice injected with RasB1 cells expressing exogenous ETV6 completely suppressed tumor growth in three of five mice tested (ETV6/CI1033)." (PMID 29455655, 2018). "We detected greater expression of ETV6 in adjacent normal colorectal tissues than in corresponding tumour tissues (PWilcoxon<0.001)." (PMID 27145994, 2016). "In this study, we found a higher protein expression level of ETV6 in normal colorectal tissues than in corresponding tumour tissues, which was consistent with the ETV6 mRNA expression results." (PMID 27145994, 2016). "Moreover, we were able to analyze sequential tumor samples in 1 ETV6::RUNX1 BCP-ALL case (ALL4) who relapsed 48 months after initial diagnosis." (PMID 37469802, 2023). "In vivo, CRISPR–Cas9-mediated knockout of ETV6 reduced the growth of subcutaneous TC32 tumours." (PMID 36658220, 2023). "In a clinical study of 25 patients who had various malignancies containing NTRK, ROS1, or ALK gene fuses and received an effective dose of entrectinib, an overall response rate of 79% with significant tumor regression in all NTRK-altered tumors (including ETv6: NTRK3 translocation) was observed." (PMID 35190738, 2022). "Finally, ETV6 is involved in tumor angiogenesis and is required for vascular development, an important pathological characteristic of GBM." (PMID 36292767, 2022). "Notably, re-stimulation with ANRU tumor cells triggered a stronger T-cell activation than re-stimulation with the neoantigen 9mer peptide, ETV6, in CD8+ T cells previously enriched by DC loaded with the same peptide." (PMID 35433456, 2022). "After 14 days of stimulating CD8+ T cells with antigen-loaded DC, tumor reactivity was analyzed by re-stimulation of CD8+ T cells with ANRU tumor cells or with the ETV6/NUP210 9mer neoantigen peptides (only for T cell that had been co-cultured with DC pulsed with the corresponding 9mer peptide)." (PMID 35433456, 2022). "To further investigate whether prognostic TFs identified through inferred activity analyses could be verified at the protein level, we performed immunohistochemical analyses in primary tumor samples from patients with uterine serous cancer (n = 31) for ETV6." (PMID 31554806, 2019). "For example, ETV6 is a negative regulator of transcription 3 (Stat3) transcription factor activity, which has the ability to mediate the inhabitation of the proliferation of tumor cells." (PMID 31405076, 2019). "In line with the ETV6 peptide being presented, we could also detect an enhanced recognition of the tumor cells by dextramer-sorted TIL specific for this peptide compared to unsorted TIL." (PMID 31921104, 2019). "When investigating the role of ETV6 in tumor progression, we hypothesized that ETV6 was inhibitory to the EMT." (PMID 29455655, 2018). "We evaluated the expression levels of the following five genes associated with DNA damage, carcinogenesis, and/or chemoprevention mechanisms: the tumor suppressors ETV6 and PTEN, the cell death regulators BCL2 and BAX (anti- and proapoptotic, respectively), and the protooncogene ABL1." (PMID 30370304, 2018). "Interestingly, the 12p13.2 breakpoint fell into the ETV6 gene, which resulted partially deleted; ETV6 is considered the main candidate tumor suppressor gene within this region." (PMID 29108298, 2017). "The ETV6 gene encodes an ETS family transcription factor that is involved in a myriad of chromosomal rearrangements found in hematological malignancies and other neoplasms." (PMID 26584717, 2015).
tumor (continued). "For instance, many clinical laboratories routinely use tumor gene panels, primarily for solid tumors, which almost invariably include the KRAS gene, enabling the incorporation of detection of individual gene alterations also from the ETV6::RUNX1 ALL samples to diagnostic workflow." (PMID 40634509, 2025). "Similarly, BCL2L14::ETV6 enhances tumor invasiveness and taxane resistance in TNBC14." (PMID 41213951, 2025). "Furthermore, in the first reported case of thyroid SC with diffuse metastatic disease at presentation, it is noteworthy that while 22% of the tumor cells had a typical ETV6 rearrangement, the remaining tumor cells showed one intact gene and one rearranged gene with gain of the red signal." (PMID 39101978, 2024). "However, fusion with ETS variant transcription factor 6 (ETV6) produces an ETV6/FLT3 oncoprotein fusion that is constitutively active and utilizes Hsp90, a chaperone known to stabilize a number of proteins required for tumor progression." (PMID 38825690, 2024). "However, 2 cases showed unbalanced ETV6 break-apart with gain of the oncogenic derivative (red signal) and with corresponding high histologic grade (moderate to marked nuclear atypia, vascular invasion and tumor necrosis)." (PMID 39101978, 2024). "This means that NTRK3 and ETV6 fusions might be causally related to the extent of the tumor mass, and a primary total thyroidectomy might be more beneficial over a subtotal one for those patients having either NTRK3 or ETV6 fusion mutation within the PTC tissue." (PMID 39409115, 2024). "We hypothesized that ETV6 played a role in GBM tumor progression." (PMID 36292767, 2022). "In this study, RT-qPCR was used, a sensitive method for detection of fusion genes in tumor samples that conventional methodologies detecting even a single molecule in lower amounts of complex samples as bone barrow, which supports the low prevalence of ETV6::RUNX1 obtained." (PMID 35685921, 2022). "We used somatic mutations from matched normal and tumor exome data and found no major differences in both the number of mutations and genomic locations between samples (except for sample ETV6.RUNX1.1 that had less mutations)." (PMID 32415257, 2020). "Therefore, ETV6 was considered a tumor suppressor, even in certain types of solid tumors." (PMID 29455655, 2018). "Moreover, most of these patients also lack ETV6 expression, suggesting a tumor suppressor function." (PMID 30341373, 2018). "Usually, when analyzing the tumor genome by CMA, aberrations larger than 5 MB and additional microdeletions involving the CDKN2A/B, BTG1, EBF1, ETV6, ERG, IKZF1, PAX5, and RB1 genes are taken into account." (PMID 39408811, 2024). "Seven genes passing these filters were involved in various aspects of tumour biology, including cell survival and DNA repair (CASP9, NDRG1, and XPA), mTOR signalling (TSC1), and transcription and RNA processing (ETV6, ISY1, and SMAD2)." (PMID 39660592, 2024). "Other rare alterations in low-grade SC include CTNNB1::ALK fusion and dual fusions of ETV6::NTRK3 and ETV6:: MAML3 in the same tumor." (PMID 38217715, 2024). "Among them, some transcription factors have been reported to mediate the EMT process, such as TBL1XR1, STAT6, ETV6, and SMARCA4, indicating their potential to regulate VM and promote tumor invasion." (PMID 38694917, 2024). "In another study, DOG1 expression was noted along the luminal surface of tumor cells in one-third of salivary SCs with atypical FISH signal patterns using break-apart and ETV6::NTRK3 fusion probes." (PMID 39101978, 2024).
tumor (continued). "IGF2BP1 is specifically expressed in ETV6::RUNX1 positive B-ALL cell lines and its knockout reduces tumor cell proliferation and prednisolone resistance in Reh cell line." (PMID 37670323, 2023). "In samples with high B7‐H3 expression, recurrent alterations included the deletion of short arm of chromosome 12 (12p), which contains tumor suppressors such as CDKN1B, ETV6, DUSP16, and miR‐613." (PMID 34562306, 2021). "After, we observed a significant positive correlation between the expression levels of ETV6 and CRKL in hepatocarcinoma tumor tissues and hepatocarcinoma cell lines, then we investigated the mutual influence between the dysexpression of ETV6 and CRKL." (PMID 32326970, 2020). "To confirm its tumor promotion effect in HCC, we measured both the overexpression and knockdown of ETV6 on the migration and invasion capacities of HCCLM3 and HuH7 cells." (PMID 32326970, 2020). "The upregulations of ETV6 and CRKL were positively correlated in both hepatocarcinoma patients’ tumorous tissues (R2 = 0.4955, P = 0.0136) and in hepatocarcinoma cells (R2 = 0.9604, P = 0.0200)." (PMID 32326970, 2020). "We found that ETV6 and CRKL were upregulated, and miR-429 was downregulated in HCC patients’ tissues and HCC cell lines compared with corresponding non-tumor liver tissues and a normal liver cell line." (PMID 32326970, 2020). "In line with the MS-results, ETV6 dextramer-stained cells expressed CD107a and displayed decreased levels of dextramer-staining when cultured with IFN-γ-treated tumor cells." (PMID 31921104, 2019). "Eighteen mutated genes were positively selected in the relapse tumour which were already present in the primary tumour (diagnosis) at low VAF (<1%) and 2 genes were relapse-specific (ETV6 and TMEM117)." (PMID 31540260, 2019). "For ANRU, in line with the MS results, the same was true for TIL enriched by ETV6 9- or 10-mer dextramers, while the MART-1-sorted TIL recognized untreated and IFN-γ-treated tumor cells to the same high extent." (PMID 31921104, 2019). "Interestingly, mammalian FoxOs and Etv6 act in similar physiological processes: both are tumour suppressors required for maintenance of adult haematopoietic stem cells; indicating that the previously-uncharacterised, functional interplay between the two factors may be evolutionarily conserved." (PMID 25232726, 2014). "Other potential tumour suppressive effects include stabilising the expression of YAP and facilitating downregulation of programmed death ligand 1 (PD-L1) on tumour cells, and in maintaining cell stemness in AML by regulating expression of ETV6 target genes." (PMID 39966556, 2025). "We identified 42 and 16 TSGs monoallelically deleted in P2 and P5, respectively, including several TSGs deleted in both tumor samples (ARHGEF10, CDKN1B, ETNK1, ETV6, LEPROTL1, NRG1, PTPN6, and WRN) and many TSGs co-deleted in the same subclone as well as across multiple subclones." (PMID 38658552, 2024). "Even though they share a common ETV6::NTRK3 fusion, these high-grade adenocarcinomas might represent a neoplasm distinct from SC by morphology and immunoprofile." (PMID 37415052, 2023). "In addition, all EpiTCer bead/DC ratios induced a higher frequency of CD107a+ CD8+ T cells compared to more traditional ways to pulse DC with antigens, such as custom made 9mer neoantigen peptides, ETV6 and NUP210, or whole tumor lysate." (PMID 35433456, 2022). "However, DC loaded with either neoantigen 9mer peptides, ETV6 or NUP210, or tumor lysate induced increased frequencies of tumor reactive CD8+ T cells when compared to the unloaded DC, MOCK." (PMID 35433456, 2022). "Next, we assessed if loading the DC with pooled ETV6 and NUP210 peptides could increase the enrichment for tumor-specific T cells to a similar extent as the one observed with EpiTCer-beads-loaded DC." (PMID 35433456, 2022).
tumor (continued). "WB results showed that compared with non-tumor liver tissues, ETV6 expression in tumorous tissues of hepatocarcinoma patients was increased by 127.6% (P = 0.0005)." (PMID 32326970, 2020). "Further workup showed the tumor to be negative for ETV6 and BCOR gene rearrangement by FISH, and negative for BCOR ITD and NTRK gene rearrangement by NGS." (PMID 32490123, 2020). "Taken together, our results indicated that ETV6, CRKL might act as tumor promoters and miR-429 as a tumor suppressor involved in the development and progression of HCC." (PMID 32326970, 2020). "A negative correlation was also established for ETV6 upregulation with miR-429 downregulation in both hepatocarcinoma patients’ tumorous tissues (R2 = 0.3090, P = 0.0254) and in hepatocarcinoma cells (R2 = 0.9655, P = 0.0174)." (PMID 32326970, 2020). "We observed a significant negative correlation between the expression level of ETV6 and miR-429 in hepatocarcinoma tumor tissues and hepatocarcinoma cell lines." (PMID 32326970, 2020). "Twenty tumor tissue samples consisting of secretory carcinomas (17 ETV6 translocation-positive and 3 ETV6 translocation-negative secretory carcinomas) were subjected to targeted deep sequencing analyses." (PMID 31822803, 2020). "ETV6 and CDKN1B are the candidate tumor suppressor genes within the region 12p13." (PMID 25213837, 2014). "The result is in accordance with the effect predicted by the in silico analysis, however it does not fit in the model of ETV6 as tumor suppressor." (PMID 24886876, 2014). "Notably, there was no additive effect on tumor recognition when stimulating CD8+ T cells with DC loaded with ETV6 combined with NUP210." (PMID 35433456, 2022). "Finally, the gene-set #2 also contained several tumour suppressors (EPHA3 and EPHB2) and proto-oncogenes (AKT1, AURKA, ETV6, MITF and PIK3CA), which expands on the observed enrichment of the immune response and suggests that this gene-set has a critical role in breast tumorigenesis." (PMID 19826428, 2009). "Moreover, ETV6 upregulation was positively correlated with CRKL upregulation, and two negative correlations were also established for ETV6 and CRKL upregulation with miR-429 downregulation in both hepatocarcinoma patients’ tumorous tissues and hepatocarcinoma cells." (PMID 32326970, 2020). "This tumor is usually positively stained with S-100, mammaglobin, CK7, MUC4, and GATA3, while in our patient the final diagnosis was based on the presence of ETV6 rearrangements which did not require immunohistochemical staining." (PMID 36186229, 2022). "Although most of the neoepitopes were still not detected by MS, the 9-mer ETV6, which was not present on untreated ANRU cells, could be detected by MS analysis on ANRU tumor cell MHC-I after IFN-γ treatment." (PMID 31921104, 2019). "In addition, MHC presentation of a neoepitope derived from the protein ETV6 was detected by MS in IFN-γ-treated, but not in untreated ANRU tumor cells." (PMID 31921104, 2019). "In summary, we report 2 cases of a high-grade tumor diagnosed as non-ITAC of the sinonasal region, characterized by overt hypercellularity, largely solid growth pattern with comedo-like necrosis, immunohistochemical positivity for p40/p63, S100, SOX10, and GATA3, with a recurrent ETV6::NTRK3 fusion." (PMID 37415052, 2023).